SORCS1 (sortilin related VPS10 domain containing receptor 1)
Synonyms: hSorCS
Tractability: Antibody: UniProt predicts a signal peptide or a membrane-spanning region; the Human Protein Atlas places it where antibodies can reach. PROTAC: its protein half-life has been measured.
Gene: Protein-coding gene on chromosome 10 (106,573,663 to 107,164,706, reverse strand). Ensembl gene ENSG00000108018.
Subcellular location: Membrane
Subcellular location (Human Protein Atlas): Cytosol; Plasma membrane
Gene Ontology:
Molecular function: protein binding; neuropeptide receptor activity; transmembrane signaling receptor activity
Biological process: neuropeptide signaling pathway; post-Golgi vesicle-mediated transport
Cellular component: membrane; Golgi apparatus
Genetic constraint (gnomAD): Loss-of-function variants: 53 observed, 131.55 expected, observed/expected ratio (o/e) 0.4, 90% interval 0.32 to 0.51. The upper end of that interval is the gene's LOEUF score, 0.51, which puts it in group 2 of 6, group 1 being the genes least tolerant of losing a copy. Missense variants: 1,325 observed, 1,458.9 expected, observed/expected ratio (o/e) 0.91, 90% interval 0.87 to 0.95. Synonymous variants: 629 observed, 577.56 expected, observed/expected ratio (o/e) 1.09, 90% interval 1.02 to 1.16.
Homologues: Orthologues: chimpanzee SORCS1 (99% identical), macaque SORCS1 (99% identical), pig SORCS1 (95% identical), mouse Sorcs1 (91% identical), rat Sorcs1 (91% identical), dog SORCS1 (91% identical), guinea pig SORCS1 (88% identical), rabbit SORCS1 (79% identical), tropical clawed frog SORCS1 (68% identical). Paralogues in human: SORCS3 (64% identical), SORCS2 (42% identical), SORL1 (23% identical), SORT1 (16% identical).
Diseases named in the same sentence as SORCS1 in open-access papers:
SORCS1 is named in the same sentence as 37 diseases in open-access papers, as found by Europe PMC text mining. Sharing a sentence is not in itself a finding about the gene and the disease. The quoted sentences say what the papers report.
diabetes (14 papers, 2011 to 2025). "Two rare missense variants (p.Pro405Arg and p.Tyr232Cys) were identified in the SORCS1 gene, which is highly expressed in the brain and has been associated with diabetes risk." (PMID 40149731, 2025). "SORSC1 has been associated with insulin secretion and diabetes risk and loss of both Sorcs1 and Sorcs3 in mutant mice caused increased adiposity and enhanced food intake, but not increased body weight." (PMID 35330733, 2022). "Two rare missense variants (p.Pro405Arg and p.Tyr232Cys) were found in SORCS1, a gene highly expressed in the brain and previously linked to diabetes risk." (PMID 35330733, 2022). "In humans, genome-wide association studies and linkage studies have shown that SORCS1 is associated with diabetes and all of diabetes complications." (PMID 31857633, 2019). "We have recently shown that deletion of Sorcs1 in mice made obese with the leptinob mutation results in diabetes and an insulin granule stability defect." (PMID 31857633, 2019). "Given the genetic association of SORCS1 with diabetes and the recently documented role for this receptor in insulin secretion, we also analyzed the systemic glucose metabolism in S1/3 KO mice fed a normal chow." (PMID 29440124, 2018). "SNPs in the human SORCS1 gene were found to be associated with fasting insulin levels in the Mexican American Coronary Artery Diseases cohort, and with diabetes risk in women of the San Antonio Family Diabetes Study." (PMID 24752583, 2014). "The gene-encoding SorCS1, SORCS1 (chromosome 10), has been associated with insulin signaling and diabetes mellitus." (PMID 22191060, 2011). "Choice of the adequate mouse model of diabetes will be key since we have observed some unexpected effects in some transgenic mouse models for amyloidosis and the effect of a deficiency of the T2D gene, Sorcs1." (PMID 30383799, 2018). "Finally, some genetic data now suggest a link between diabetes and AD, as in the case of the insulin degrading enzyme gene or, more recently the SorCS1 gene which is thought to regulate Aβ metabolism (Laneet al., 2010;Laneet al., 2013)." (PMID 27303627, 2016). "Genes SORCS1 and SKAP2 have relationship with diabetes type 1, diabetes mellitus type 2, cardiovascular diseases, and Edema." (PMID 28079101, 2017). "In contemplating this result in the context of the AD/T2D association with SORCS1, this observation raised the possibility that Sorcs1-/- mice crossed with AD model mice (here, APP/PSEN1 mice) might manifest overt diabetes if stressed by the accumulation of cerebral amyloid." (PMID 26916443, 2016).
Alzheimer disease (12 papers, 2010 to 2023). A progressive, neurodegenerative disease characterized by loss of function and death of nerve cells in several areas of the brain leading to loss of cognitive function such as memory and language. "SORCS1 is implicated in beta amyloid processing and Alzheimer disease and attention deficit hyperactivity disorder, which again are considered human-specific neurological conditions." (PMID 23185133, 2012). "SORCS1 has been previously implicated in neurodegeneration by genetic association with Alzheimer's disease as well as with APP processing whereby reduced expression of SORCS1 is associated with increased γ-secretase processing and Aβ levels possibly as a result of altered trafficking." (PMID 24833721, 2014). "Haplotype frequencies (>1%) of the five SNPs rs17277986, rs6584777, rs10884402, rs7078098 and rs950809 in SorCS1 gene and their relative risks for Alzheimer’s disease." (PMID 23700427, 2013). "The variations of SORCS1 gene may play potential key roles in late-onset Alzheimer’s disease (LOAD)." (PMID 23700427, 2013). "Thus, our data suggest a role for SorCS1 in the rescue of AβO-induced NRX dysfunction and synaptic pathology, providing the basis for a novel potential therapeutic strategy for Alzheimer’s disease." (PMID 36697254, 2023).
type 2 diabetes (10 papers, 2010 to 2025). "The suggestive region identified by RHM on SSC14 contained SORCS1, which is implicated in obesity-induced type 2 diabetes." (PMID 40813973, 2025). "Other studies, especially genome-wide association studies (GWAS), have linked sortilin expression and function and SorCS1 to glucose metabolism and the risk of type 2 diabetes development." (PMID 38339069, 2024). "The objective of this study was to elucidate the functional consequence of the Thr52Ile single nucleotide polymorphism in the pro-domain of the Sorcs1 gene that has been associated with type 2 diabetes." (PMID 31857633, 2019). "Jointly, these findings support the notion that type 2 diabetes associated Sorcs1 plays a role in complex gene–environment interactions in this disease." (PMID 29440124, 2018). "As Sorcs1 mutation drives an obesity-regulated diabetic phenotype in animals, these findings have significant implications for the human-associated gene variants and substantiates its role as a genetic contributor to type 2 diabetes." (PMID 31857633, 2019). "While the phenotype of Sorcs1 knock out mice provided an opportunity to study the consequence of a complete loss-of-Sorcs1, it does not necessarily provide true insight into the functional consequences of the non-synonymous Thr52Ile Sorcs1 variants associated with type 2 diabetes." (PMID 31857633, 2019). "Hence, further studies in other populations are needed to elucidate whether these novel sequence variants, especially rs1358030 near the SORCS1 locus, affect glycemic control in type 2 diabetes." (PMID 21294870, 2011). "We genotyped 1,486 subjects with type 2 diabetes from a Norwegian population-based cohort (HUNT2) for single-nucleotide polymorphisms (SNPs) located near the BNC2, SORCS1, GSC and WDR72 loci." (PMID 21294870, 2011). "Therefore, it is not surprising that impairments in SorCS1 activity are strongly associated with Type 1 and Type 2 diabetes." (PMID 36397124, 2022). "Considering our results in light of the previous reported results and features for SORCS1, we can not refute a possible link between SORCS1 and glycemic control in type 2 diabetes." (PMID 21294870, 2011).
Obesity (7 papers, 2014 to 2025). Accumulation of substantial excess body fat. "Another study investigating genetic variants in 72 individuals with obesity also found two rare missense SORCS1 variants of unknown significance." (PMID 35330733, 2022). "More studies are needed to investigate the molecular mechanisms of SORCS1 and the possible contribution of this gene to early-onset obesity." (PMID 35330733, 2022). "As we found in the survival analyses, 5 DE mRNAs (SORCS1, FLRT3, HIBADH, CATSPER1, and MAP3K8) and 5 DE miRNAs (hsa-miR-3130-2, hsa-miR-148b, hsa-miR-2681, hsa-miR-4487, and hsa-miR-3613) of obesity-related ccRCC were found in VAT." (PMID 34621242, 2021). "Taken together, ablation of SORCS1 and SORCS3 expressions in mice on a normal chow resulted in a distinct metabolic phenotype with a shift in energy substrate preference, diminished usage of lipids as metabolic fuel, and increased adiposity in the absence of classical obesity manifestation." (PMID 29440124, 2018).
bipolar disorder (3 papers, 2011 to 2013). A disorder of the brain that causes unusual shifts in mood, energy, activity levels and the ability to carry out day-to-day tasks. "These include GFOD1, which is associated with attention deficit hyperactivity disorder (ADHD), DLGAP1 which is associated with schizophrenia, DOCK9 associated with bipolar disorder, and SORCS1 which is associated with memory." (PMID 24151499, 2013). "Although highly speculative at present, one genetic study reported a de novo duplication of the chromosomal region 10q23 encoding SORCS1 and SORCS3 in an individual with bipolar disorder." (PMID 24069373, 2013).
amyloid (2 papers, 2016 to 2018). "In general, unexpectedly, there was a trend for gene targeting of Sorcs1-/- to mitigate, not exacerbate, the metabolic, behavioral, and amyloid pathologies." (PMID 26916443, 2016).
colorectal cancer (2 papers, 2021 to 2025). A primary or metastatic malignant neoplasm that affects the colon or rectum. "SORCS1 was found to be hypermethylated in colorectal cancer tissues, and reduced SORCS1 expression was identified as an independent prognostic factor in colorectal cancer patients." (PMID 34326275, 2021).
diabetes type 1 (2 papers, 2011 to 2017). "In addition to a strong association with HbA1c, the BNC2 and SORCS1 risk alleles have revealed associations with mean glucose levels in type 1 diabetes, suggesting that these genetic variations affect HbA1c through their effects on glucose." (PMID 21294870, 2011).
Huntington disease (2 papers, 2017 to 2019). Huntington disease (HD) is a rare neurodegenerative disorder of the central nervous system characterized by unwanted choreatic movements, behavioral and psychiatric disturbances and dementia. "Further work on generating a knock-out mutant of SorCS1 will shed more light on better understanding the role of this gene in Huntington’s disease." (PMID 28920088, 2017).
tobacco use disorder (2 papers, 2017 to 2023). "Gene-disease association shows SORCS1, SKAP2, and CELSR2 genes are related with genetic susceptibility, and genes SORCS1 and PCDH10 are related with tobacco-use disorder." (PMID 28079101, 2017).
celiac disease (1 paper, 2019). An autoimmune genetic disorder with an unknown pattern of inheritance that primarily affects the digestive tract. "One study reported an association of celiac disease (CE), a condition thought to primarily involve MHC/HLA genes, with SORCS1 variants." (PMID 31450785, 2019).
cerebral amyloid angiopathy (1 paper, 2016). "Interestingly, Aβ was deposited as cerebral amyloid angiopathy (CAA) in large and small blood vessels within the brains of male and female APP/PSEN1 mice as well as Sorcs1 -/- x APP/PSEN1 mice." (PMID 26916443, 2016).
cervical adenocarcinoma (1 paper, 2021). An adenocarcinoma arising from the cervical epithelium. "CircSPIDR was found to sponge miR-431-5p, thereby de-repressing sortin-related VPS10 domain-containing receptor 1 (SORCS1) and cubilin (CUBN) and inhibiting the development of cervical adenocarcinoma." (PMID 34326275, 2021).
cognitive decline (1 paper, 2023). "TOMM40 and SORCS1 were associated with both amyloid and tau CSF biomarkers, while BCHE was associated with cognitive decline." (PMID 37629144, 2023). "We associated TOMM40 and SORCS1 with both amyloid and tau pathologies, whereas BCHE was associated with cognitive decline." (PMID 37629144, 2023).
Glucose intolerance (1 paper, 2016). Glucose intolerance (GI) can be defined as dysglycemia that comprises both prediabetes and diabetes. "Glucose intolerance was apparent in Sorcs1 -/- mice tested at 20 weeks of age." (PMID 26916443, 2016).
Hyperglycemia (1 paper, 2018). An increased concentration of glucose in the blood. "Though the mutant mice showed a mild impairment in glucose tolerance at young age (12 weeks; Fig EV2B and C), this phenotype did not progress to hyperglycemia during aging (Fig EV3A), suggesting that SORCS1 and SORCS3 are dispensable for glycemic control in chow‐fed mice." (PMID 29440124, 2018).
Impaired glucose tolerance (1 paper, 2016). An abnormal resistance to glucose, i.e., a reduction in the ability to maintain glucose levels in the blood stream within normal limits following oral or intravenous administration of glucose. "Male APP/PSEN1, Sorcs1 -/-, and Sorcs1 -/- x APP/PSEN1 mice continued to display impaired glucose tolerance compared to WT mice." (PMID 26916443, 2016).
Insulin resistance (1 paper, 2011). Increased resistance towards insulin, that is, diminished effectiveness of insulin in reducing blood glucose levels. "Two studies have also demonstrated modest evidence for association between SNPs in SORCS1 and fasting insulin, insulin sensitivity and insulin resistance in humans." (PMID 21294870, 2011).
Niemann-Pick disease type C (1 paper, 2009). NPC is a complex lipid storage disease mainly characterized by the accumulation of unesterified cholesterol in the late endosomal/lysosomal compartment. "Interestingly, a recent gene expression profiling comparison of normal and Niemann Pick disease type C (NPC) patient fibroblasts revealed changes in several genes important for membrane traffic including RAB20 and SorCS1." (PMID 19381295, 2009).
polycystic kidney disease (1 paper, 2018). A usually autosomal dominant and less frequently autosomal recessive genetic disorder characterized by the presence of numerous cysts in the kidneys leading to end-stage renal failure. "The members of the SorCS subfamily (SorCS1, SorCS2, and SorCS3) all contain a region rich in leucine residues that consists of a polycystic kidney disease (PKD) domain (pdb-id 1WGO) and an additional 202 residues of unknown fold." (PMID 30061605, 2018).
prion disease (1 paper, 2014). A transmissible disease that is caused by a protein that is able to induce abnormal folding of normal cellular proteins, leading to characteristic spongiform brain changes, which are associated with neuronal loss without an inflammatory response. "STMN2 was identified as a prion disease susceptibility factor in vCJD, and ZBTB38 and SORCS1 were identified in a meta-analysis of vCJD, sCJD and kuru resistance GWAS data." (PMID 24833721, 2014).
synucleinopathies (1 paper, 2023). "Thus, in future studies, it will be important to address whether and how SorCS1 overexpression and anti-NRX1β treatment rescue α-syn PFF-induced pathology in culture and in vivo for the development of novel therapeutic strategies for synucleinopathies." (PMID 37048156, 2023).
cancer (2 papers, 2023 to 2024). A tumor composed of atypical neoplastic, often pleomorphic cells that invade other tissues. "We further integrated our methylation results with RNA-seq data, and we identified 11 genes, including six related to immune functions (AHR, LRFN5, NTRK2, RSPO2, SAMSN1, and TFEC), and three related to cancer (SLC12A5, SORCS1, and TP63)." (PMID 39795948, 2024).
tumor (2 papers, 2015 to 2021). "Finally, many of the genes down-regulated by EZH2 GOF in this study that modulate ECM-adhesion/signaling display altered expression or have been ascribed roles in tumor biology (e.g. NRCAM, CEACAM1, SORCS1, ADAM23, MME)." (PMID 25671303, 2015).
SORCS1 also shares sentences with these, for which no sentence is quoted: schizophrenia (3 papers); attention deficit-hyperactivity disorder (2); autism (2); cardiovascular diseases (1); Cerebral atrophy (1); clubfoot (1); cognitive deficits (1); infection (1); Intellectual disability (1); neurological disease (1); opioid dependence (1); Parkinson disease (1); polycystic ovary syndrome (1).